CCL17 (C-C motif chemokine ligand 17)
Description:
Chemokine, which displays chemotactic activity for T lymphocytes, preferentially Th2 cells, but not monocytes or granulocytes. Therefore plays an important role in a wide range of inflammatory and immunological processes. Acts by binding to CCR4 at T-cell surface. Mediates GM-CSF/CSF2-driven pain and inflammation. In the brain, required to maintain the typical, highly branched morphology of hippocampal microglia under homeostatic conditions. May be important for the appropriate adaptation of microglial morphology and synaptic plasticity to acute lipopolysaccharide (LPS)-induced neuroinflammation (By similarity). Plays a role in wound healing, mainly by inducing fibroblast migration into the wound (By similarity).
Synonyms: SCYA17; TARC; ABCD-2; A-152E5.3
Tractability: Small molecule: it has a binding pocket of medium quality. Antibody: UniProt places it where antibodies can reach, with high confidence; its Gene Ontology location is reachable by antibodies, with high confidence; UniProt predicts a signal peptide or a membrane-spanning region.
Target class: Secreted protein
Gene: Protein-coding gene on chromosome 16 (57,404,767 to 57,416,063, forward strand). Ensembl gene ENSG00000102970.
Subcellular location: Secreted
Pathways (Reactome):
Immune System: Dectin-1 mediated noncanonical NF-kB signaling
Signal Transduction: Chemokine receptors bind chemokines
Gene Ontology:
Molecular function: protein binding; chemokine activity; signaling receptor binding
Biological process: cell chemotaxis; cell-cell signaling; chemotaxis; immune response
Cellular component: extracellular region
Genetic constraint (gnomAD): Loss-of-function variants: 5 observed, 5.07 expected, observed/expected ratio (o/e) 0.99, 90% interval 0.51 to 1.8. That is too few expected variants to judge how well the gene tolerates losing a copy. Missense variants: 64 observed, 67.97 expected, observed/expected ratio (o/e) 0.94, 90% interval 0.77 to 1.16. Synonymous variants: 23 observed, 29.77 expected, observed/expected ratio (o/e) 0.77, 90% interval 0.56 to 1.1.
Homologues: Orthologues: chimpanzee CCL17 (100% identical), macaque CCL17 (88% identical), pig CCL17 (73% identical), guinea pig CCL17 (66% identical), rat Ccl17 (64% identical), mouse Ccl17 (62% identical), zebrafish ccl38a.5 (23% identical), zebrafish ccl38.1 (22% identical), zebrafish ccl38a.4 (20% identical), zebrafish ccl38.6 (18% identical). Paralogues in human: CCL22 (35% identical), CCL13 (29% identical), CCL15 (29% identical), CCL7 (29% identical), CX3CL1 (29% identical), CCL14 (28% identical), CCL18 (28% identical), CCL4 (28% identical), CCL19 (27% identical), CCL23 (27% identical), CCL26 (27% identical), CCL4L2 (27% identical), and 14 more.
Diseases named in the same sentence as CCL17 in open-access papers:
CCL17 is named in the same sentence as 254 diseases in open-access papers, as found by Europe PMC text mining. Sharing a sentence is not in itself a finding about the gene and the disease. The quoted sentences say what the papers report.
atopic dermatitis (87 papers, 2011 to 2025). "The elevation of CCL17 has been associated with the progression of skin inflammatory diseases such as atopic dermatitis and also reported in patients with post kala azar dermal leishmaniasis." (PMID 40277930, 2025). "Along with its ligands, CCR4 has been associated to the pathophysiology of allergic skin illnesses including atopic dermatitis (AD), where elevated blood levels of CCL17 are linked to disease activity." (PMID 37259456, 2023). "The main pathogenic factor in atopic dermatitis (AD) is Th2 inflammation, and levels of serum CCL17 and CCL22 are related to severity in AD patients." (PMID 37110740, 2023). "Chronic inflammatory skin diseases, such as atopic dermatitis, are caused by the accumulation of immune cells and the overproduction of chemokines, including CCL17 and CCL22, due to the activation of pro-inflammatory cytokines secreted from keratinocytes." (PMID 34451592, 2021). "The homeostatic chemokine, CCL17 (TARC) has been associated with human diseases affecting various organs such as ulcerative colitis (UC), atopic dermatitis (AD), idiopathic pulmonary fibrosis (IPF) and asthma." (PMID 24339934, 2013). "In atopic dermatitis, tumour necrosis factor-α, which is secreted by keratinocytes, increases the production of chemokine CCL17, causing an increase in the AQP3 expression level." (PMID 22315629, 2012). "Three potentially pathogenic chemokine pathways have been identified in atopic dermatitis (CCL17/CCL22-CCR4, CCL27-CCR10, and CX3CL1-CX3CR1), and two in psoriasis (CCL20-CCR6 and CCL17/CCL22-CCR4), where one of them seems to be common." (PMID 40149440, 2025). "Patients with acute myofascial pain have higher levels of CCL22, and in atopic dermatitis, increasing serum CCL17 correlates with increasing pain." (PMID 41291326, 2025). "In atopic dermatitis, serum TARC/CCL17 is the most promising biomarker for assessing disease severity." (PMID 40529811, 2025). "In Japan, serum CCL17 levels have been commercially measured since 2008 as a biomarker for atopic dermatitis." (PMID 40269953, 2025). "The results showed that CSSH reduced pro-inflammatory cytokines (IL-1β, IL-6, IL-8, MCP-1 and CXCL10) and atopic dermatitis-related cytokines (IL-4, CCL17, MDC and RANTES) in TNF-α/IFN-γ-induced HaCaT cells." (PMID 38931136, 2024). "After 2,4-dinitrochlorobenzene (DNCB) induction in mice with atopic dermatitis, FA effectively reduced the symptoms and serum levels of CCL17 and CCL22." (PMID 37110740, 2023). "TNF-α/IFN-γ, which is extensively employed in atopic dermatitis simulations, acts on HaCaT cells and induces them to release chemokines and cytokines, such as IL-6, IL-8, CCL17, and CCL22." (PMID 37110740, 2023). "In atopic dermatitis, IL-9 levels correlated with clinical severity, IgE levels, and C-C motif chemokine ligand 17 (CCL17) levels." (PMID 37398641, 2023). "CCL13 (MCP-4) has been implicated in inflammatory processes in asthma, and CCL17 (TARC) is a biomarker of atopic dermatitis severity with a reported case of transient increase after FIA." (PMID 35202004, 2022). "CCL17 is elevated in bronchoalveolar lavage from idiopathic pulmonary fibrosis and positively correlates with disease activity in atopic dermatitis." (PMID 34943853, 2021). "CCL17 and CCL22 have been reported closely associated with Th2 cell-mediated inflammatory diseases such as atopic dermatitis." (PMID 34451592, 2021). "CCL17 has been studied predominantly in skin diseases, such as atopic dermatitis; however, elevated levels have also been reported in SLE patients." (PMID 34831390, 2021). "Of possible relevance to these observations, IL-23 and CCL17 can induce skin inflammation, the former via TNF, and both are implicated clinically in psoriasis and atopic dermatitis." (PMID 32471485, 2020). "It was shown that in humans with atopic dermatitis, a decreased circulation of Th17 (IL-17+) cells correlated with increased levels of CCL17." (PMID 29931394, 2018).
atopic dermatitis (continued). "Based on these data, the Japanese Pharmaceutical and Medical Devices Agency has approved a serum CCL17 ELISA kit (Alaport® TARC) as a clinical examination tool for atopic dermatitis." (PMID 27376063, 2016). "Several studies have reported elevated serum levels of CCL17 in human atopic dermatitis subjects with CCL17 thought to be produced by keratinocytes." (PMID 25981299, 2015). "CCL17 is established to be involved in three Th2-dominant diseases: bronchial asthma, atopic dermatitis, and eosinophilic pneumonia." (PMID 23705860, 2013). "Several association studies using genetic variants of genes CCL17 and CCR4 in the CCR4 pathway have been conducted to discover genetic components in the pathogenesis of atopic dermatitis." (PMID 22125604, 2011). "CCL22 is upregulated in lesional atopic dermatitis skin compared with healthy skin, and keratinocytes in the epidermal layer of AD skin express CCL17 and CCL22." (PMID 22125604, 2011). "Atopic dermatitis is caused by chronic inflammation of the skin tissue, and the onset of atopic dermatitis is closely related to various inflammatory mediators such as IL-4, IL-13, CCL5, CCL17, and CCL22." (PMID 39599592, 2024). "Moreover, MCP-1/CCL2 and IL-8 are closely linked to the onset and severity of chronic skin inflammation, with TARC/CCL17 levels showing a positive correlation with atopic dermatitis severity in affected individuals." (PMID 38786617, 2024). "In addition, the production of CCL17 was increased in the epidermis of CHS lesions, while the serum CCL17 levels were reported to be connected with atopic dermatitis." (PMID 34831296, 2021). "Several blood molecules have been investigated in human studies as potential biomarkers of atopic dermatitis, including TARC/CCL17, macrophage-derived chemokine, IL-22, pulmonary and activation-regulated chemokine, sIL-2R, soluble E-selectin, C-reactive protein, and IL-16." (PMID 34677385, 2021). "Excess CCL17 mediates severe inflammation in atopic dermatitis and osteoarthritis." (PMID 33707490, 2021). "TARC/CCL17 has been proposed as a candidate gene for conferring susceptibility to Th2 associated with allergic diseases and is deeply involved in the etiology of atopic dermatitis and bronchial asthma." (PMID 33265990, 2020). "Co-expression of CCL17 and CCL22 has been reported in human type 2 diseases such as in the bronchoalveolar fluid of asthmatics and serum of atopic dermatitis patients." (PMID 41159038, 2025). "To ensure that these changes were not related to the severity of AD, we compared the scoring of atopic dermatitis (SCORAD) values and the concentration of CCL17, an AD marker, in our study groups." (PMID 41438035, 2025). "TNF-α has been reported to promote the production of CCL17 and CCL22 in keratinocytes, inducing features similar to atopic dermatitis." (PMID 38533495, 2024). "MDC/CCL22 acts as a Th2 skewed chemoattractant, upregulates TARC/CCL17 production, and has been found to correlate with atopic dermatitis disease activity." (PMID 38582943, 2024). "Thymus and activation-regulated chemokine (TARC; CCL17) is a T-helper-2 chemokine that reflects atopic dermatitis (AD) disease activity." (PMID 39917426, 2024). "Thymus- and activation-regulated chemokine (TARC, also known as CCL17) is used as a biomarker for atopic dermatitis." (PMID 37761302, 2023). "According to previous studies, epithelial cells and keratinocytes damaged by atopic dermatitis produce proinflammatory cytokines (such as TNF-α, IL-1β, IL-6, and IL-8) and chemokines (such as CCL17/TARC, CCL22/MDC)." (PMID 36793948, 2023). "Our date showed that VAE inhibited CCL17 and CCL22 levels in TNF-α/IFN-γ-stimulated HaCaT keratinocytes and DNCB-induced atopic dermatitis animal models." (PMID 36793948, 2023). "We have shown that H4R antagonists inhibit the production of the Th2 chemokines CCL17 and CCL22 in human monocyte-derived Langerhans cells from patients with atopic dermatitis." (PMID 36275674, 2022).
atopic dermatitis (continued). "In atopic dermatitis, damaged epithelial cells and keratinocytes produce proinflammatory cytokines and chemokines such as TNF-α, IL-1β, IL-6, IL-8, CCL17, and CCL22." (PMID 36158872, 2022). "In prior studies, chemokines such as CCL17 and CCL22 were suggested as potential therapeutic targets for chronic skin inflammation, including atopic dermatitis." (PMID 34451592, 2021). "Other chemokines such as TARC/CCL17, MDC/CCL22, and RANTES/CCL5 are typical Th2 cell-secreted chemokines predominantly expressed by keratinocytes involved in atopic dermatitis." (PMID 34073317, 2021). "Consistently, we and others have also shown that the CCR4 ligands CCL17 and CCL22 are highly expressed in allergic diseases such as atopic dermatitis and bronchial asthma." (PMID 34771703, 2021). "CCL17 and its receptor CCR4 play a central role in the pathogenesis of endotoxin shock and inflammatory diseases such as atopic dermatitis and asthma." (PMID 33648537, 2021). "CCL17 and CCL22 are key chemokines inducing Th2 chemotaxis and are strongly elevated in the serum of patients with Th2-driven atopic dermatitis." (PMID 34721430, 2021). "In particular, we and others have shown that the levels of CCL17 and CCL22 in the blood are highly elevated in patients with atopic dermatitis and correlate well with disease severity and treatment response." (PMID 34771703, 2021). "First, HaCaTs were used to verify the mRNA expression regulation activity of CCL17 and CCL22, which are biomarkers of atopic dermatitis." (PMID 34451592, 2021). "Strong positive correlations between the levels of CCL17, CCL22, and total IgE in serum of patients with AD and SCORing Atopic Dermatitis (SCORAD) have also been reported." (PMID 22125604, 2011). "In addition, CCL17/TARC is a biomarker of progression in several diseases, including atopic dermatitis and asthma, attracting Th2 cells to the site of inflammation." (PMID 40236699, 2025). "In addition, the gene expression levels of IL-4, IL-13, CXCL10, CCL5, CCL17, and CCL22, which are related to atopic dermatitis, were significantly decreased by HCFE in DPM-stimulated HaCaT cells." (PMID 39599592, 2024). "In addition, the expression of IL-4, IL-13, CXCL10, CCL5, CCL17, and CCL22, which are atopic dermatitis mediators, increased 2- or 3-fold in HaCaT cells treated with DPM compared with that in the control group." (PMID 39599592, 2024). "Thymus and Activation-Regulated Chemokine (TARC), also named CCL17 (CC chemokine ligand 17), is a CC-chemokine that is mostly known as the key regulator of Th2-mediated inflammation in allergic asthma and atopic dermatitis." (PMID 36756279, 2023). "CCL17 was involved in the process of pulmonary fibrosis through CCR4-positive alveolar lymphocytes and macrophages, and the level of CCL17 correlated positively with disease activity and was used as a biomarker for monitoring the severity of atopic dermatitis." (PMID 34943853, 2021). "In this article, we will focus upon the chemokine CCR4 and its ligands CCL17 and CCL22, which are postulated to play key roles in the pathogenesis of allergic asthma, atopic dermatitis and a variety of cancers, including breast cancer, gastric cancer renal cell cancer and lymphoma." (PMID 25981299, 2015). "By contrast, atopic dermatitis and Th2-related genes, including Il4, Il5, Il13 and Il31 were lowly expressed or not detected at all, and other atopic dermatitis-related transcripts (Ccr4, Ccl17, Ccl24) were not significantly differentially expressed." (PMID 38528069, 2024). "Although the exact mechanism and treatment for atopic dermatitis have not been found, controlling the excessive production of TARC/CCL17 and MDC/CCL22 may be the key to treatment." (PMID 35335198, 2022).
atopic dermatitis (continued). "In recent studies, increased levels of CC-chemokines, such as thymus, activation-regulated chemokine (TARC/CCL17), and CC-chemokine macrophage-derived chemokine (MDC/CCL22) were observed in the skin of patients with chronic skin inflammatory diseases, including atopic dermatitis." (PMID 34451592, 2021). "In contrast, although the chemokine CCL17/TARC is thought to contribute to allergic disorders, the −431 C/T SNP in the gene encoding CCL17 increases chemokine expression without enhancing susceptibility to atopic dermatitis." (PMID 28178200, 2017). "Furthermore, we and others have demonstrated that the serum levels of CCL17 and CCL22 substantially increase in patients with allergic diseases and that the serum levels of CCL17 correlate particularly with the disease activities of atopic dermatitis." (PMID 27376063, 2016). "Similarly, CCR4-involving cell-cell communication, with the ligands CCL5, CCL17, CCL22, also showed diseased organ specificity, but in nonlesional atopic dermatitis and psoriatic skin." (PMID 40809141, 2024). "However, it should be acknowledged that elevated serum CCL17/TARC levels are not specific to DIHS/DRESS and can also be found in many other skin diseases, such as atopic dermatitis (AD), bullous pemphigoid (BP), and mycosis fungoides (MF)." (PMID 34204146, 2021).
asthma (76 papers, 2005 to 2025). "Elevated CCL17 is associated with various pulmonary conditions including idiopathic pulmonary fibrosis, asthma and COPD and cigarette smoke-induced pulmonary inflammation." (PMID 36809921, 2023). "CCL17, is a thymus and activation-regulated chemokine, associated with chronic pulmonary inflammation in asthma." (PMID 29254155, 2017). "TSLP and TARC/CCL17 expression is associated with airway obstruction in patients with asthma." (PMID 29670037, 2018). "The pathogenesis of asthma, which is an allergic lung disease, is associated with a variety of allergens such as house dust mite, pollen, and mould, IgE containing serum IgE and allergen-specific-IgE, and inflammatory cytokines including thymus and activation-regulated chemokine (TARC)/CCL17." (PMID 29755573, 2018). "The significance of CCL22 and CCL17 is further affirmed in murine models of asthma, where the utilization of specific neutralising antibodies enables the reduction of airway hyperresponsiveness and allergic inflammation." (PMID 40577410, 2025). "More recently, it has been demonstrated that CCL17 levels were positively correlated with depression and anxiety levels in patients with asthma." (PMID 38308225, 2024). "For key cytokine levels associated with asthma in the lung, TSLP/OVA administration led to significant increases of lung CCL17 and IL-13 levels in mice in G2 group relative to G1 group." (PMID 39726595, 2024). "CCL17 (TARC) and CCL22 (MDC) are ligands for CCR4, while CCL1 (I-309) binds CCR8, and these three ligands have been associated with asthma." (PMID 37259416, 2023). "The chemokine CCL17, which contributes to the Th2 cell recruitment in asthma, was elevated in HDM-PBS group compared to PBS-PBS group (p < 0.05)." (PMID 32582180, 2020). "In our study, eotaxin and CCL-17 protein act as the most selective markers because their levels in blood serum samples vary depending by asthma severity." (PMID 31438916, 2019). "Higher relative abundance of these bacteria is furthermore associated with an airway immune profile dominated by reduced TNF-α and IL-1β and increased CCL2 and CCL17, which itself is an independent predictor for asthma." (PMID 31676759, 2019). "In asthma, increased CCL17 production by lung macrophages attract CCR4+ Th2 T lymphocytes, which play a central role in orchestrating airway inflammation." (PMID 30197642, 2018). "Many other pathways were also identified that are regulated by IL-13 and relevant to asthma pathogenesis (e.g. CCL17, CCL26, CTGF, FCER1A, KITLG, MUC2, NOS2, TLR3)." (PMID 29367592, 2018). "CCR4 and its ligand CCL17 are up-regulated in the airways of asthmatic patients after challenge and contribute to the Th2 cell recruitment in asthma." (PMID 26003185, 2016). "Previously, an important role for CCR4 and its ligand CCL17 in Th2 T cell recruitment has been demonstrated in asthma." (PMID 25849971, 2015). "Both B202 and B225 antibodies neutralize CCL17 in vivo as demonstrated by reduction of methacholine-induced airway hyperreactivity in the A. fumigatus model of asthma." (PMID 24339934, 2013). "A role for CCL17 in fungus-induced asthma has been previously established using either CCR4 KO mice or treatment with polyclonal CCL17-specific antibodies." (PMID 24339934, 2013). "Though mice treated with the anti-CCL17 surrogate antibodies in the A. fumigatus model showed improvement in asthma related symptoms in vivo, effectiveness of the antibodies was not equivalent in vitro." (PMID 24339934, 2013). "A recent study using a humanized model of asthma showed a critical role for DC-derived CCL17 and CCL22 in attracting Th2 cells and inducing airway inflammation." (PMID 22125604, 2011). "Reduction of the CCR4 ligand, CCL17 by H4R antagonist in a comparable study also suggests a direct inhibition of CCR4 + Th2 cells, a sub-population implicated in asthma pathogenesis." (PMID 20573261, 2010).